PPM1D (protein phosphatase, Mg2+/Mn2+ dependent 1D)
Diseases named in the same sentence as PPM1D in open-access papers (continued):
Sharing a sentence is not in itself a finding about the gene and the disease.
tumor (continued). "To characterize the role of PPM1D in tumor development, we constructed genetically engineered C57BL/6N mice overexpressing WIP1 through pronuclear injection of the human PPM1D gene controlled by the rat tyrosine hydroxylase (TH) promoter." (PMID 34771656, 2021). "We therefore backcrossed the C57BL/6N PPM1D +/− mice for eight generations with 129 × 1/SvJ mice, which are more prone to tumor formation, in order to establish a near 100% 129 × 1/SvJ background." (PMID 34771656, 2021). "We observed that overexpression of Ppm1d in blood cells in mice accelerated the growth of solid tumors, whereas deletion of Ppm1d in blood cells suppressed tumor growth." (PMID 34131120, 2021). "Other tumor manifestations observed in several PPM1D-positive mice were spleen, liver, lung, and lymph node metastases." (PMID 34771656, 2021). "Recent work suggests that the level of PPM1D/Wip1 activity in immune cells affects tumor progression." (PMID 34131120, 2021). "PPM1D is a phosphatase which promote growth and its numerous downstream targets are important tumor promoting factors." (PMID 34470916, 2021). "In this work, we show that PPM1D is overexpressed in tumor-infiltrating neutrophils, both in humans and mice, and its genetic deletion or chemical inhibition in myeloid cells increases their anti-tumor phenotypes and suppresses tumorigenesis." (PMID 34131120, 2021). "Based on the expression of specific markers, we studied the expression of PPM1D, its association with prognosis of HCC, while level of the various tumor-infiltrating immune cells (TIICs) in this research." (PMID 34470916, 2021). "Our results show that PPM1D overexpression results in tumor development in mice subjected to DNA stresses." (PMID 34771656, 2021). "In summary, we provide the first in vivo evidence that truncated PPM1D can promote tumor growth and modulate sensitivity to chemotherapy." (PMID 31659152, 2019). "Overall, our results reveal a promising approach for the targeting of PPM1D mutant tumors, and define a critical link between oncogenic driver mutations and NAD metabolism, which can be exploited for tumor-specific cell killing." (PMID 31439867, 2019). "It will be interesting to determine the contribution of truncated PPM1D to tumor development using the BRAF-V600E mouse model." (PMID 31659152, 2019). "PPM1D small interfering (si)RNA-induced PPM1D silencing was performed in CRC cell lines to assess the effect of PPM1D on tumor cell proliferation and invasion in vitro." (PMID 25009596, 2014).
tumor (continued). "Second, we combined Ppm1d with the relatively strong oncogene platelet-derived growth factor B (PDGFB) to increase tumor penetrance, but PDGF receptor alpha (PDGFRA) may be a more faithful alteration found in human DMG10." (PMID 41394550, 2025). "In this study, we also tested the hypothesis that the accumulation of PPM1D due to proteasome inhibition contributes to tumor cell survival, similar to the increased malignancy observed with C-terminal deletion mutants of PPM1D." (PMID 40931354, 2025). "Furthermore, the role of PPM1D in DNA damage response and tumour suppression gives rise to questions regarding potential long-term health implications, which necessitate further investigation." (PMID 40630121, 2025). "We hypothesized that the combination of the proteasome inhibitor bortezomib and the PPM1D inhibitor GSK2830371 could effectively suppress malignant tumor progression." (PMID 40931354, 2025). "Investigating PPM1D inhibitors in the context of tumor cell senescence may open up new treatment options for patients, and such strategies may have fewer side effects." (PMID 39702569, 2024). "Interestingly, in several human tumor cell lines, Ppm1d protein levels progressively increased from G1 to G2 phases and then decreased during mitosis, revealing the importance of Ppm1d in regulating the nature of the cellular response to DDR." (PMID 39702569, 2024). "Importantly, these cells formed colonies in the soft agar and tumours in the xenograft models confirming the ability of active PPM1D to transform the cells." (PMID 39237765, 2024). "Perhaps the combined use of PPM1D inhibitor and senolytics, which selectively eliminate senescent cells, may be an effective strategy for different tumor types." (PMID 39702569, 2024). "A selective and potent allosteric inhibitor with acceptable pharmacokinetic properties could be applied to tumors with PPM1D alterations and combined with DNA damaging modalities to augment anti-tumor activity." (PMID 35773251, 2022). "Finally, in both smoothened-overexpressing and PTCH+/- MB models, PPM1D knockout dramatically suppressed de novo tumor formation." (PMID 35747808, 2022). "Our result is consistent with these earlier findings, which suggest that PPM1D mutations may be related to PARP inhibitor resistance and thus to poorer tumour responses." (PMID 36583171, 2022). "Notably, this set contained several activated DEGs from sets of those found with cells producing uS10mut1, uS10mut2, or uS10mut3, including tumor-associated genes such as GADD45A, PPM1D, MDM2, and CREBRF." (PMID 35682850, 2022). "According to the GEPIA and TIMER databases, PPM1D mRNA expression in HCC tissue remarkably associated with the expression of marker gene due to TAMs, tumor-infiltrating Monocytes, M1 Macrophage, M2 Macrophage, DCs, Th and Treg, while the association was not remarkable in CHOL." (PMID 34470916, 2021). "Normally elevated expression of PPM1D gene is found within the thalamus, oculomotor nuclear complex of the midbrain, which is the location where tumor originated, globose nucleus, nucleus subceruleus, superior olivary complex, and central medullary reticular group." (PMID 34257334, 2021). "This suggests the vital contribution of the PPM1D in adjusting tumor-infiltration of the Th cells." (PMID 34470916, 2021).
tumor (continued). "To test whether the tumor-suppressive characteristic of Ppm1d-depleted immune cells is transferable to wild-type mice, we transplanted bone marrow (BM) cells isolated from wild-type or Ppm1dKO2/KO2 mice into lethally irradiated wild-type mice." (PMID 34131120, 2021). "Within the period of 50 weeks of age we did not observe any tumor growth in the colon of Ppm1dT/+ mice suggesting that truncated PPM1D does not represent the tumor-initiating mutation leading to ISCs transformation." (PMID 31659152, 2019). "Based on our observations that mutant PPM1D blocks this pathway via tumor-specific NAPRT silencing, NA supplementation may be an effective approach to further enhance the therapeutic index associated with NAMPT inhibition." (PMID 31439867, 2019). "All the low level PPM1D mutations in blood samples were identified by conventional sequencing, but no corresponding mutations in the tumor tissues were observed, as suggested in the previous reports." (PMID 31242196, 2019). "The reason why the increased stability of PPM1D in the mouse model shifts the tumor burden from the small intestine to the colon remains unclear." (PMID 31659152, 2019). "In addition these genes increased resistance to therapy targeting HER2 but targeting HER2 and PPM1D and/or miR21 reduced the tumor burden of the cells." (PMID 31442252, 2019). "In addition, truncated PPM1D promoted tumor growth in the colon in Apcmin mice and diminished survival." (PMID 31659152, 2019). "In summary, we provide the first in vivo evidence that truncation of PPM1D contributes to tumorigenesis and may affect response of tumor cells to chemotherapy." (PMID 31659152, 2019). "As these agents are commonly used to treat tumors that harbor PPM1D mutations (e.g., DIPG), they could be combined with NAMPT inhibitors to further enhance tumor-selective cytotoxicity." (PMID 31439867, 2019). "By these means, PPM1D enhances oncogenic transformation and tumor growth." (PMID 23050965, 2012). "Moreover, we hypothesized that PPM1D accumulation upon proteasome inhibition contributes to chemoresistance in tumor cells and provided evidence that the combination of a proteasome inhibitor and a PPM1D inhibitor enhances antitumor efficacy." (PMID 40931354, 2025). "Besides, they implied that expression of PPM1D might regulate tumor immunity through modulating the infiltration of the immune cells of HCC." (PMID 34470916, 2021). "Tumor development was significantly delayed with median time to tumor development (≥0.1 mL tumor volume) more than doubled (33 days median, vs. 15 days) in the PPM1D-shRNA knockdown group compared to animals injected with control shRNA-transfected cells (p < 0.001)." (PMID 34885154, 2021).
tumor (continued). "Moreover, the neutralization of 4-1BBL and OX-40L on the surface of cells with specific antibodies in Ppm1dLysM-cre mice attenuated the tumor-suppressive effect of Ppm1d deletion in myeloid cells and significantly accelerated the tumor growth to the same ratio as in wild-type mice." (PMID 34131120, 2021). "Moreover, tumor organoids derived from colon of the ApcminPpm1dT/+ mice were less sensitive to 5-fluorouracil when compared to ApcminPpm1d+/+and the sensitivity to 5-fluorouracil was restored by inhibition of PPM1D." (PMID 31659152, 2019). "Our observations suggest a possible new mechanism by which Akt can attenuate the activity of several tumor suppressors and disrupt the DNA damage response to enhance cellular survival, proliferation, and chemoresistance through positive regulation of its newly discovered effector, PPM1D." (PMID 23050965, 2012). "This modification allowed the exosomes, loaded with panobinostat and PPM1D siRNA, to cross the BBB, accumulate at the tumor site, and be internalized by DIPG cells via cRGD, releasing their cargo through endosomal escape." (PMID 40806198, 2025). "It suppresses tumor proliferation through mechanisms involving the TRPM7 channel and PPM1D phosphatase, while inducing apoptosis via modulation of the AKT/mTOR and Bax pathways." (PMID 41367628, 2025). "MAP3K1, PPM1D, LMTK3, and TGFB1 levels were significantly elevated across all tumor subtypes, with the highest concentrations consistently observed in TNBC (e.g., TGFB1: 544.92 ± 29.81 pg/mL; MAP3K1: 15.44 ± 0.56 ng/mL)." (PMID 41465262, 2025). "This siRNA specifically knocks down the expression of PPM1D in DIPG cells, thereby inhibiting tumor proliferation, which is in line with previous research reports." (PMID 35585670, 2022). "High expression of PPM1D mRNA in HCC samples correlated with high α-FP level (≥400 ng/L), larger tumor diameters (≥5 cm) and more advanced TNM stage (TNM stage 3 and 4)." (PMID 23556002, 2013). "For CDKN1A, TIGAR, and PPM1D, although some genetic alterations were observed in BC cell lines and tumor samples, no significant changes in gene expression were detected across different BC subtypes." (PMID 41345520, 2025). "Myc staining was observed in Ppm1d-flex-6 tumors but not in normal brain tissues or in tumors from littermate controls, confirming tumor-specific expression of truncated Ppm1d in the presence of Cre." (PMID 41394550, 2025). "In one of these cases, other mutations such as PPM1D and NF1, which were identified in the tumor tissue samples, were also not detected in the CSF samples." (PMID 38388726, 2024). "As cell growth regulators, PP2Cs may act as tumor suppressors (ILKAP, PHLPP) or function as activators of oncogenesis (PPM1D)." (PMID 39702569, 2024). "Concerning copy number aberrations (CNAs), the top amplified genes in the samples from the primary tumor were ERBB2 (6/19, 32%), AURKA, PPM1D (4/19, 21%), and FGFR1 (3/19, 16%), while in the metastatic samples ERBB2 (7/17, 41%), CDK12, FGFR1 (4/17, 24%), and AURKA, MDM4, MYC (3/17, 18%)." (PMID 36717329, 2023). "A functionalized macrophage exosome-based nano-drug delivery system loaded with Panobinostat and PPM1D siRNA effectively kills Pontine Gliomas (DIPG) tumor cells in vitro and achieves significant tumor growth inhibition and prolonged survival time in orthotopic DIPG-bearing mice." (PMID 37525212, 2023).
tumor (continued). "The tumor suppressor activity of p38α has been studied in relation to the occurrence of the overexpression of several negative modulators of p38 MAPK signaling in various human tumor types, such as the phosphatases PPM1D and DUSP26 and ASK1 inhibitors." (PMID 35008796, 2021). "Furthermore, a gene fusion of PPM1D and BCAS3 was also found to be present in one NB tumor, subsequently resulting in accumulating PPM1D expression levels." (PMID 34945759, 2021). "Most of the supporting evidence for oncogenic properties of PPM1D comes from cell-based assays or from the knock-out mouse model, however, contribution of the truncated PPM1D to tumor growth has not been addressed in vivo so far." (PMID 31659152, 2019). "Additionally, the inhibition of PPM1D could be a promising anti-tumor strategy to treat PPM1D-altered UCB patients, and intriguingly, all PPM1D alterations were only presented in advanced UCB tumors." (PMID 36818471, 2022).
infection (10 papers, 2008 to 2024). The state of being infected such as from the introduction of a foreign agent such as serum, vaccine, antigenic substance or organism. "Wild-type (WT) Cas9-expressing OCI-AML2 and two isogenic PPM1D-mutant lines were transduced with the Human Improved Whole Genome Knockout CRISPR library V1 containing 90,709 guide RNAs (gRNAs) targeting 18,010 human genes at low multiplicity of infection (MOI~0.3)." (PMID 38896450, 2024).
hematologic malignancies (6 papers, 2015 to 2025). "Ultimately, our data allow us to speculate that prophylactic inhibition of PPM1D may prevent individuals exhibiting CH from acquiring additional driving mutations and thus protect them from the development of hematological malignancies." (PMID 37709843, 2023). "Truncating PPM1D mutations in non-CRC tumors, including hematological malignancies, may arise by different mechanisms than MMR defects." (PMID 31659152, 2019).
digestive tumors (1 paper, 2021). "Based on TIMER database, we analyzed the association of PPM1D mRNA expression with the infiltrating immune cells in 8 types of digestive tumors inclusive of HCC." (PMID 34470916, 2021).
neurodevelopmental disorder (1 paper, 2020). A behavioral and cognitive disorder with onset during the developmental period that involves impaired or aberrant development of intellectual, motor, or social functions. "The incidental variants were detected in genes PPM1D (syndromic neurodevelopmental disorders)." (PMID 32779812, 2020).
PPM1D also shares sentences with these, for which no sentence is quoted: liver cancer (5 papers); Sepsis (5); intrahepatic cholangiocarcinoma (4); lymph node metastasis (4); viral infection (4); ovarian clear cell cancer (3); renal carcinoma (3); adenocarcinoma (2); adenocarcinomas of the breast (2); bladder cancer (2); brain cancer (2); chronic lymphocytic leukemia (2); colitis (2); diabetes (2); esophageal squamous cell carcinoma (2); Fanconi anemia (2); inflammatory bowel disease (2); Intellectual disability (2); lymphopenia (2); pancreatic adenocarcinoma (2); pancreatic neuroendocrine tumor (2); abscess (1); acute kidney injury (1); acute lymphoblastic leukemia (1); acute promyelocytic leukemia (1); adenoid cystic carcinoma (1); adenoma (1); amyotrophic lateral sclerosis (1); anxiety disorder (1); B cell deficiency (1).
A further 51 diseases each share a sentence with PPM1D in 1 paper.